IL10 (interleukin 10)
Diseases named in the same sentence as IL10 in open-access papers (continued):
Sharing a sentence is not in itself a finding about the gene and the disease.
lymph node metastasis (18 papers, 2011 to 2025). "The increased mRNA expression of IL-10 was also associated with lymph node metastasis, lymphovascular invasion, pleural invasion and poor differentiation (p < 0.0001, p = 0.010, p = 0.017 p = 0.001, respectively)." (PMID 21595995, 2011). "Furthermore, the expression of ILT4 or IL-10 was associated with less number of Tumor Infiltrating Lymphocytes (TILs) (p = 0.004 and 0.018, respectively) and more lymph node metastasis (p = 0.046 and 0.035, respectively)." (PMID 24762057, 2014). "Multivariate Cox regression confirmed intraoperative blood loss and lymph node metastasis as poor prognostic factors, likely via TGF-β/IL-10 immunosuppression." (PMID 41184923, 2025). "Studies have shown that elevated levels of IL-10 in CRC tissues are closely associated with tumor staging, lymph node metastasis, and poor prognosis." (PMID 38562480, 2024). "High levels of Tregs, monocytes, IL10 and chemokines (such as CCL12, CCL2) were also shown to associate with a higher risk of TC lymph node metastases and overall worse prognosis." (PMID 37173925, 2023). "IL-1β, IL-6 and IL-10 immunostaining was significantly higher in tumour and lymph node metastasis than in MSR squamous epithelium (p<0.001)." (PMID 31870104, 2019). "The concentrations of plasma IL-10 in the patients with lymph node metastasis (27.95±5.7 pg/ml) were significantly higher compared with the patients with no lymph node metastasis (22.66±4.4 pg/ml) (P=0.01)." (PMID 24765208, 2014). "Expression level of ILT4 or IL-10 was much higher in cases with lymph node metastasis (p = 0.046 and 0.035, respectively)." (PMID 24762057, 2014). "In humans, IL-10 serum levels increase over time during CRC progression, correlating with poor prognosis, while high levels of ARG-1 were associated with stage III–IV CRC tumors and lymph node metastasis." (PMID 33036138, 2020). "In addition, with the development of LSCC, higher IL-10 plasma levels and higher OR values of the −592 A/C, −819 T/C, −1082 A/G polymorphisms were found in the advanced LSCC patients and the patients with lymph node metastasis." (PMID 24765208, 2014). "The expression levels of IL-2 (P ═ 0.010), IL-4 (P ═ 0.028), IL-10 (P ═ 0.011), IL-12p70 (P ═ 0.034), IL-17 (P ═ 0.024), tumor necrosis factor (TNF)-α (P ═ 0.003), and interferon (IFN)-γ (P ═ 0.007) were related to lymph node metastasis." (PMID 38920620, 2024). "The results indicated a significant correlation between IL-2 (P ═ 0.025), IL-4 (P ═ 0.005), IL-8 (P ═ 0.009), IL-10 (P ═ 0.017), IL-12p70 (P ═ 0.002), IL-17 (P < 0.001), TNF-α (P < 0.001), and IFN-γ (P ═ 0.026) and lymph node metastasis." (PMID 38920620, 2024). "CCL2 was reported to promote lymph node metastasis and recurrence in PTC, and IL-10 was related to tumor size and invasion in THCA." (PMID 37798795, 2023). "High levels of IL-10 in TAM significantly correlated with stage, tumor size, lymph node metastasis, lymphovascular invasion or histologic poor differentiation." (PMID 21595995, 2011). "Our study suggested that increased IL-10 expression of TAM in NSCLC patients correlated with late stage disease (stage II, III and IV), lymph node metastases, pleural invasion, lymphovascular invasion and poor differentiation." (PMID 21595995, 2011). "The results showed that there is a statistically significant correlation between the expression level of IL-2 (P ═ 0.010), IL-4 (P ═ 0.028), IL-10 (P ═ 0.011), IL-12p70 (P ═ 0.034), IL-17 (P ═ 0.024), TNF-α (P ═ 0.003), and IFN-γ (P ═ 0.007) and lymph node metastasis." (PMID 38920620, 2024). "NSCLC patients with lymph node metastases had higher serum IL-10 levels than NSCLC patients without lymph node metastases (18.03 (10.56–24.22) pg/ml vs. 15.92 (11.32–22.17) pg/ml; respectively, P < 0.05)." (PMID 29361917, 2018).
lymph node metastasis (continued). "Multivariate Cox regression analysis was performed stepwise including age, gender, primary tumor (colon or rectum), UICC (I/II or III/IV), depth of tumor invasion (T category 1/2 or 3/4), differentiation (1/2 or 3/4), lymph node metastasis (N category), Foxp3 (%), Treg (%), TGF-ß (%), and IL-10 (%)." (PMID 23382847, 2013). "Gaur P discovered that the expression levels of Interleukins 4 (IL-4) and IL-10 and Transforming Growth Factor (TGF-β) in the central region of OSCC are closely related to the activity of Th2 cells, which results in the inhibition of immune function, local infiltration, and lymph node metastasis." (PMID 34925510, 2021). "In addition, the contents of IL-10 were dramatically decreased in the Nx stage when compared to patients with N0 stage of PTC patients, indicating the existence of adaptive immunity in patients with lymph node metastasis." (PMID 32050977, 2020). "Furthermore, plasma IL-10 concentrations were significantly higher in the patients with lymph node metastasis (27.95±5.7 pg/ml) compared with those without metastasis (22.66±4.4 pg/ml) (P=0.01)." (PMID 24765208, 2014).
mucositis (18 papers, 2010 to 2026). Mucositis is inflammation and damage of the mucous membranes lining the mouth and other parts of the gastrointestinal (GI) tract. "Three confounders were identified in the present study, as our data demonstrated that mucositis, weight loss, and smoking pack-years impacted levels of IL-6 and IL-10, whereas smoking pack-years had a strong influence on IL-18 serum levels, corroborating some earlier findings." (PMID 35682983, 2022). "There remains, however, a huge gap in the knowledge to recognise whether anti-inflammatory cytokines such as IL-4, IL-10, IL-11, and IL-1ra are essential tools in downregulating the inflammatory response associated with mucositis." (PMID 22973511, 2012). "Higher IL-6 and IL-10 levels in PICF of individuals with mucositis in comparison to healthy individuals were observed." (PMID 37355561, 2023). "Considering the evaluation in the saliva, higher levels of IL-6 and IL-10 were found in individuals with mucositis in comparison to healthy individuals." (PMID 37355561, 2023). "This evidence strongly supports the notion that IL-10 is in fact a crucial cytokine with anti-inflammatory properties that remains to be investigated in the setting of chemotherapy-induced mucositis." (PMID 22973511, 2012). "Contrarily, anti-inflammatory mediators including IL-10 could attenuate the symptoms of mucositis and inhibit its progression by limiting secretion of proinflammatory cytokines." (PMID 35677366, 2022). "Changes in IL-6 and IL-10 concentrations were significantly associated with mucositis, body weight change, and smoking pack-years, but not with the modality of treatment or tumor stage." (PMID 35682983, 2022). "In contrast, Dio efficaciously suppressed the expression of NF-κB downstream pro-inflammatory cytokines, including TNF-α, IL-6 and IL-1β in the ileums of CDDP-induced mucositis rats, and substantially promoted the production of the immunoregulatory mediators IL-10." (PMID 35457248, 2022). "We were unable to detect any correlation between IL-1, TNF-α, and IL-10 levels and mucositis." (PMID 20184737, 2010). "However, a number of interesting non-significant trends were observed, For example, levels of IL-10, an anti-inflammatory cytokine, in saliva at each dose level compared to baseline were higher in patients with high grade mucositis compared to those with low grade mucositis." (PMID 22537315, 2012). "Patients were evaluated for mucositis according to WHO common toxicity criteria, and blood samples were drawn for inflammatory (IL-1, IL-6, IL-8, TNF-α) and anti-inflammatory (IL-10) cytokine levels before and during treatment." (PMID 20184737, 2010). "The IL‐10 concentration, typically elevated in patients with peri‐implant diseases compared to healthy subjects and in patients with mucositis rather than peri‐implantitis, suggested a relationship with the peri‐implant tissue inflammatory response." (PMID 40101934, 2025). "The aim of this study was to evaluate the levels of salivary biomarkers IL-1β, IL-10, RANK, OPG, MMP-2, TG-β and TNF-α in individuals with diagnosis of peri-implant mucositis in the absence or presence of periodontal and peri-implant maintenance therapy (TMPP) over 5 years." (PMID 30810638, 2019). "A relationship between high levels of IL-6 and a high grade of mucositis at week 4 was found (p = 0.081), but no such relationship between IL-1, TNF-α, IL-8 or IL-10 level and mucositis grade was shown." (PMID 20184737, 2010). "Unlike, in general, the IL-10 levels in PICF and saliva were reduced in peri-implantitis disease in comparison to health and mucositis status." (PMID 37355561, 2023).
psoriatic arthritis (18 papers, 2010 to 2025). Joint inflammation associated with psoriasis. "A direct causal link between IL-10 and lipoprotein levels was also suggested from a randomized placebo controlled clinical trial of recombinant human IL-10 in patients with psoriatic arthritis." (PMID 27579193, 2016). "In our psoriatic arthritis patient study, the increase in IL‐10 production caused by the probiotic mixture could be responsible for decreased B‐cell numbers, given IL‐10's role in suppressing B‐cell activation, proliferation, and differentiation." (PMID 41211170, 2025). "Interleukin-17 and IL-12 along with the TH1 cytokines (TNF-α, IL-1B, and IL-10) have been found in higher levels in psoriatic arthritis synovium and IL-17 and IL-23 have been implicated in the potentiation of osteoclastogenesis and bone erosion in psoriatic arthritis joints." (PMID 23209897, 2012). "We have shown that IL-10-producing Bregs in psoriatic arthritis(PsA) were decreased and inversely correlated with IFNγ+T cells (TH1 cells) and IL-17+ T cells (TH17 cells)." (PMID 32185301, 2018). "Increased serum levels of many cytokines were indeed found in other rheumatic diseases: notably psoriatic arthritis (IL-6, IL-7, IL-10, and IFN-γ, TGF-β, or TNF-α) suggesting that such rises may reflect inflammation rather than being disease specific." (PMID 28057980, 2016). "Interestingly, patients with psoriatic arthritis have been shown to exhibit elevated IL-10 serum levels, which may represent a compensatory mechanism aimed at modulating systemic inflammation in individuals with both cutaneous and articular involvement." (PMID 40731810, 2025). "Notably, targeting IL-17 is effective in psoriatic arthritis and tolDC deviate T-cells in CIA from IL-17 to IL-10 production." (PMID 27117700, 2017).
psychosis (18 papers, 2018 to 2026). "In this context, examining the interleukins (IL-1β, IL-2, IL-6, IL-10) in these patients offers a promising path toward understanding the early immunological disturbances associated with psychosis." (PMID 41008291, 2025). "The main inflammatory markers associated with clinical outcome in psychosis were interleukin (IL)-6, IL-10, and C-reactive protein (CRP)." (PMID 33679475, 2021). "Existing meta-analyses have suggested that patients with psychosis may exhibit an imbalance between pro-inflammatory cytokines (e.g., IL-1β, IL-6) and anti-inflammatory cytokines (e.g., IL-10), which could underlie immune dysregulation in the early stages of the illness." (PMID 41008291, 2025). "The maternal immune activation model of psychosis leads to decreased IL-10 levels at both the maternal fluids and in the foetal brain, causing a set of psychotic-like behaviour disturbances, which are all prevented by IL-10 overexpression in the macrophages of pregnant dams." (PMID 30686977, 2018). "In our study, IL-10 levels were found to be significantly elevated in the group of patients with FEDN psychosis compared to the healthy control group." (PMID 41008291, 2025). "Differences between peripheral and central IL-10 signalling have been proposed as a factor in varying clinical presentations of psychosis; our observations may be consistent with this hypothesis, but longitudinal data would be needed to explore it." (PMID 41008291, 2025). "This study further illuminates the immunological profile of patients experiencing a first episode of psychosis, showing that IL-1β, IL-2, and IL-10 are not only significantly altered compared to the healthy controls, but are also associated with specific dimensions of the clinical picture." (PMID 41008291, 2025). "Psychosis in amphetamine-dependent women during early cessation is associated with increases in IL-10, TNF-α, and IL-5 (the latter cytokine was not measurable in our research)." (PMID 37996407, 2023). "In first-episode psychosis, interferon-γ (IFN-γ), IL-1RA, IL-1β, IL-6, IL-8, IL-10, IL-12, sIL-2R, TGF-β, and TNF were all significantly increased, and levels of IL-4 were significantly decreased." (PMID 32256401, 2020). "However, several studies, including meta-analyses, found elevated levels of IL-6, IL-10, and TNF-α in first-episode drug-naïve (FEDN) psychosis patients and first-episode SCZ patients, the majority of whom were using antipsychotics." (PMID 37491201, 2023). "Other potential state markers are IL-4 and IL-10, although in this case, only in chronic schizophrenia and not in the first episodes of psychosis." (PMID 36830990, 2023). "Although IL-6 and TNF-α have been already previously suggested as a possible important target for patients with treatment-resistant psychosis and with prevalent negative syndrome, the findings of increased IL-10 were more unexpected." (PMID 33667853, 2021). "The results of the ROC analysis in our study showed that IL-2, IL-1β, and IL-10 had significant discriminatory ability in distinguishing the patients with FEDN psychosis from the healthy controls, while IL-6 did not demonstrate a statistically significant value." (PMID 41008291, 2025). "In psychosis, reduced IL-10 levels were negatively correlated with negative and cognitive symptoms." (PMID 30686977, 2018).
vasculitis (18 papers, 2013 to 2025). "A differential expression pattern among interleukins has been reported, with PR3-ANCA vasculitis associated with IL-10 and IL-32 elevation." (PMID 33023023, 2020). "In this prior study in MHV-68-infected IFNγR−/− mice, Serp-1 treatment reduced vasculitis, inflammation, and pulmonary consolidation and hemorrhage with associated increases in IL-10, suggesting a potential beneficial effect for IL-10 in MHV-68 infection in IFNγR−/− mice." (PMID 30249047, 2018). "Thus, further investigations are necessary to elucidate the mechanism underlying KD-related vasculitis and the efficacy of IL-10 in this disease." (PMID 29765083, 2018). "Jung and colleagues dissected the association between interleukin 10 (IL10) and vasculitis: the comparison of 21 studies led to the identification of SNPs that increased the susceptibility risk of AAV and specifically GPA." (PMID 39057087, 2024). "First, we clearly showed the preventive effect of IL-10 supplementation on vascular inflammation and lethality in CAWS-induced vasculitis; however, the therapeutic efficacy of IL-10 in established vasculitis remains to be examined." (PMID 29765083, 2018). "To explore the factors involved in the inhibitory effects of IL-10 in CAWS-induced vasculitis, we assessed the expression of inflammatory cytokines and fibrosis-related factors in the heart." (PMID 29765083, 2018). "Next, to examine the effect of the AAV-mediated induction of IL-10 on KD-related vasculitis, we treated mice with CAWS, 2 weeks after the induction of AAV-IL-10." (PMID 29765083, 2018). "Because interleukin-10 (IL-10) was identified as a negative regulator of cardiac inflammation in a murine model of KD induced by Candida albicans water-soluble fraction (CAWS), we investigated the effect of IL-10 supplementation in CAWS-induced vasculitis." (PMID 29765083, 2018). "Because CAWS is a mannoprotein-β-glucan complex and has been recently shown to be recognized by C-type lectin receptor Dectin-211, we examined whether Dectin-2 is involved in the inhibitory effects of IL-10 in CAWS-induced vasculitis." (PMID 29765083, 2018). "Thus, we assume that IL-10 is a potential candidate for anti-inflammatory therapy in KD-related vasculitis." (PMID 29765083, 2018). "However, in the spleen and liver of IL-10−/− mice B. abortus infection resulted in development of an acute inflammatory response characterized by vasculitis and thrombosis, necrosis, and influx of neutrophils." (PMID 23818855, 2013). "Serum concentrations of BAFF, APRIL, and other cytokines, including IL-4, IL-6, IL-10, and IL-13, can be implicated in the differentiation of B-cell lineages, while significant increases in BAFF, APRIL, IL-4, and IL-6 were observed in patients with ANCA-vasculitis." (PMID 40430184, 2025). "Complications are often due to vasculitis and endothelial cell injury, with a cytokine storm involving IL-6, TNF alpha, and IL-10 contributing to multi-organ failure." (PMID 39737257, 2024). "In PR3-ANCA vasculitis, levels of TNF-α, thromboxane A2 (TXA2) and CD14 were increased, while in MPO-ANCA vasculitis the C-C motif chemokine receptor 8 (CCR8) levels was higher and IL-10 expression was lower compared to controls." (PMID 33023023, 2020). "There are some other molecules like IL-10, which have a distinct expression level between PR3-ANCA and MPO-ANCA vasculitis." (PMID 33023023, 2020). "In the present study, we clearly showed that the AAV-mediated induction of IL-10 almost completely inhibits vascular inflammation and cardiac remodeling in CAWS-induced vasculitis." (PMID 29765083, 2018). "In prior work the Myxomavirus-derived anti-inflammatory serpin, Serp-1, improved survival, reducing vasculitis and pulmonary hemorrhage in MHV-68-infected IFNγR−/− mice with significantly increased IL-10." (PMID 30249047, 2018). "All mouse strains (B6, Mir155-/-, Il10-/-, and DKO) had subacute vasculitis/perivasculitis of vascularized stromal tissues at the base of the heart." (PMID 26252010, 2015).
vasculitis (continued). "Also, serum IL-10 did neither differ between AAV patients with and those without relapsing vasculitis or between individuals with and those without renal or upper/lower respiratory involvement, respectively." (PMID 31286195, 2019).